INS (insulin)
Diseases named in the same sentence as INS in open-access papers (continued):
Sharing a sentence is not in itself a finding about the gene and the disease.
Insulin resistance (continued). "Insulin resistance, characterized by a diminished response to insulin in regulating glucose levels in the body, has been shown to affect left ventricular ejection fraction (LVEF), particularly after submaximal work." (PMID 38540729, 2024). "Previous research has shown that insulin treatment can induce insulin resistance in cultured cells, resulting in a reduction in cellular responsiveness to the IIS pathway and down-regulation of associated receptors and receptor substrates." (PMID 39075596, 2024). "The effects of berberine on the glycemic profile included significantly reduced fasting blood glucose, insulin levels, glycated hemoglobin (HbA1c), and insulin resistance index (HOMA-IR)." (PMID 39407506, 2024). "Compared with the WT mice, glucose intolerance, insulin resistance and hyperinsulinemia were all greatly improved in the IKO mice, indicating that NCoR1 deficiency in IECs results in an insulin-sensitive phenotype." (PMID 39807334, 2024). "This condition includes heightened fat mobilization, suppressed glucose metabolism, diminished insulin sensitivity, and the onset of insulin resistance." (PMID 39518840, 2024). "The results showed that synbiotic supplementation significantly lowered fasting blood glucose, insulin concentration, and insulin resistance, while enhancing insulin sensitivity." (PMID 38931292, 2024). "The proposed explanation for such results was the favorable properties of omentin-1 via anti-inflammatory and insulin signaling pathways and, hence, diminishing insulin resistance and better blood glucose control." (PMID 39139157, 2024). "Systematic evaluation of glucose control, body mass index, blood pressure, insulin secretion and insulin resistance is leveraged to identify patients who are likely to receive the greatest metabolic benefit from common antidiabetic drugs." (PMID 38177805, 2024). "IFG is primarily caused by hepatic insulin resistance and disturbed first-phase insulin secretion, whereas IGT primarily results from muscle insulin resistance, impaired first- and second-phase insulin secretion, and reduced β-cell sensitivity to glucose." (PMID 38999727, 2024). "In HFD-induced obese mice, apigenin (0.005% w/w, p.o. for 16 weeks) attenuated IR and inflammation and significantly decreased levels of FBS, plasma insulin, and the homeostatic index of insulin resistance (HOMA-IR)." (PMID 38629096, 2024). "For example, cytokines and mediators released during the inflammatory response can disrupt insulin signalling pathways, leading to insulin resistance and glucose metabolism disorders." (PMID 38386717, 2024). "In the absence of preexisting metabolic aberrations, infection does not result in hyperglycemia because the pancreas compensates for skeletal insulin resistance by secreting more insulin." (PMID 39107476, 2024). "Insulin resistance (IR) is a complex metabolic disorder characterized by impaired cellular responses to insulin, primarily affecting skeletal muscle, liver, and adipose tissue." (PMID 38920999, 2024). "Insulin resistance (IR) is defined as a clinical state in which cells fail to respond normally to the insulin hormone and also denotes impaired insulin sensitivity that impede glucose disposal." (PMID 39518747, 2024). "In non-diabetic males, we calculated the homeostasis model assessment index (HOMA-R), an estimate of insulin resistance, from serum fasting insulin and glucose." (PMID 39014506, 2024). "In previous studies, both insulin resistance status improvement and circulating insulin reduction have been shown to increase serum SHBG levels, thereby reducing the blood level of free testosterone in patients with PCOS." (PMID 39357046, 2024). "Similar to type 2 diabetes mellitus, gestational diabetes is characterized by increased insulin resistance by up to 30-40% and reduced insulin secretion in response to hyperglycemia." (PMID 39035594, 2024).
Insulin resistance (continued). "Insulin resistance (IR) is characterized by the inability of exogenous or endogenous insulin to perform its role in glucose uptake and utilization." (PMID 39021592, 2024). "In contrast, homeostasis model assessment (HOMA) is a traditional indicator used to determine insulin resistance and insulin sensitivity." (PMID 38969755, 2024). "Apelin synthesis in adipocytes is elicited by insulin and its plasma level is increased in relation to insulin resistance and hyperinsulinemia." (PMID 37930396, 2024). "It is associated with hyperglycemia due to the progressive decline in insulin-secreting β–cells and a reduction in β–cell volume, together with varying degrees of insulin resistance." (PMID 38396842, 2024). "Insulin resistance denotes a diminished ability of insulin to facilitate glucose uptake by the target tissues." (PMID 39271468, 2024). "This metabolic derangement is connected with insulin resistance (reduced efficiency of insulin in glucose utilization in insulin-sensitive tissues, such as muscle, adipose tissue, the liver, and the brain)." (PMID 38540315, 2024). "Moreover, such deficiency of insulin, resulting either from absolute insulin deficiency or from brain insulin resistance, may promote the accumulation of Aβ aggregates and the hyperphosphorylation of tau proteins because the physiological effects of insulin can oppose these processes." (PMID 39062768, 2024). "We used established in vitro cell lines to model insulin sensitivity and insulin resistance and provide a comprehensive overview of the molecular changes." (PMID 39562547, 2024). "While plasma FFA levels were not different among the groups, CDN1163 significantly decreased fasting plasma insulin levels and restored glucose tolerance and homeostatic model assessment for insulin resistance score to control levels." (PMID 38729350, 2024). "This systematic review and meta-analysis aimed to assess the effect of SCFA interventions on fasting glucose, fasting insulin, and homeostatic model assessment of insulin resistance (HOMA-IR)." (PMID 37290429, 2024). "Circulating EPDR1 was positively correlated with body mass index (BMI), BMI z‐score, insulin, glucose, homeostatic model assessment insulin resistance index (HOMA‐IR), triglycerides, white blood cells, and neutrophils." (PMID 40626250, 2024). "Their anti-diabetic properties have been demonstrated by their reported activities of regulating glucose-lipid metabolic homeostasis, promoting insulin secretion and enhancing insulin sensitivity as shown in vivo and in vitro models of insulin resistance." (PMID 38799166, 2024). "An ipITT performed at the end of the studies showed that after 8 weeks WD-fed mice were unable to respond to exogenously administered insulin and, thus, had insulin resistance as compared to the insulin-sensitive CD-fed mice." (PMID 38550379, 2024). "The two groups were similar concerning HbA1c, fasting insulin or homeostatic model assessment for insulin resistance, and lipid levels; fasting glucose levels were marginally lower in CS than in NFAI (p < 0.001)." (PMID 38775914, 2024). "The metabolic score for insulin resistance (METS-IR), a novel non-insulin-based tool, is gaining attention for quantifying insulin resistance using multiple metabolic parameters." (PMID 39514584, 2024). "GHRH/GH signaling is crucial in modulating insulin sensitivity as reduced GH levels due to impaired GHRH activity can exacerbate insulin resistance, contributing to the development of type 2 diabetes." (PMID 39560873, 2024). "Insulin resistance in the brain was defined as the inability of neurons or glia cells to respond to insulin action, resulting in impairments in the synaptic, metabolic, and immune response functions." (PMID 39683565, 2024). "This pathology is defined as glucose intolerance and is characterised as an insufficient insulin response and insulin resistance." (PMID 39518962, 2024).
Insulin resistance (continued). "The significance of insulin resistance and impaired insulin secretion prior to or following transplantation has been highlighted in recent studies investigating the mechanism of PTDM." (PMID 38674437, 2024). "The aim of the study is to analyze the newly calculated indexes Glu/Zn, Ins/Zn, and HOMA-IR/Zn as surrogate markers to explore the correlation between serum zinc status and some indexes of insulin sensitivity and insulin resistance." (PMID 39596259, 2024). "As observed in other insulin-resistant mouse models, this increase in β cell mass is likely to act as a compensatory mechanism to counteract the insulin resistance in SKO mice." (PMID 38745956, 2024). "An intriguing aspect of brain insulin resistance in AD is the interplay between insulin/p-IRS/PI3K/Akt signaling and the upregulation of BDNF." (PMID 39769243, 2024). "Women had lower mean weight, ALM, ALM/weight, VAT, and serum myostatin levels (p < 0.05), and similar mean insulin sensitivity by Matsuda index and insulin resistance by HOMA‐IR, than men." (PMID 39261976, 2024). "CNIs also reduce the expression of cell surface glucose transporter 4 (GLUT4) and decrease insulin-stimulated glucose uptake in adipocytes, potentially leading to peripheral insulin resistance." (PMID 39346923, 2024). "Animal experiments have found that overdosing of glargine insulin for 8 weeks in mice with normal glucose tolerance also induced insulin resistance and type 2 diabetes." (PMID 38334891, 2024). "It has also been demonstrated that insulin sensitivity and glucose tolerance were impaired in A1R KO mice, whereas A1R overexpression can protect mice from insulin resistance." (PMID 38794716, 2024). "Inflammatory cytokines, such as TNF-α and IL-6, can interfere with insulin signaling pathways, promoting insulin resistance and impairing glucose uptake by neurons and glial cells." (PMID 39594624, 2024). "While insulin resistance is a cardinal hallmark of T2DM, it ultimately drives a compensatory increase in insulin secretion and β-cell hypertrophy." (PMID 39194692, 2024). "The two main frequently cited hallmarks of T2DM are impaired insulin secretion due to dysfunction of the pancreatic β-cell and impaired insulin action due to insulin resistance." (PMID 39493778, 2024). "The relevance of IGKV2D-28 is explored within the context of GDM, which mirrors the complex pathology of T2DM, which is marked by insulin resistance and inadequate insulin secretion." (PMID 39408856, 2024). "The HFHFrHC diet-feeding induced insulin resistance in WT mice, whereas Mlkl−/− and Mlkl+/− mice displayed significantly improved insulin sensitivity compared to WT mice on the same diet." (PMID 38474061, 2024). "To investigate the metabolic phenotyping of dKO mice under various dietary conditions, we assessed glucose and insulin levels, as well as insulin resistance markers, in both male and female mice." (PMID 39440369, 2024). "Insulin resistance is a metabolic disorder in which pathological sensitivity of adipocytes (adipose tissue cells) and cardiomyocytes (cardiac muscle cells) to insulin is observed." (PMID 39796443, 2024). "The main pathological feature of prediabetes is impaired blood glucose regulation; both IFG and IGT have insulin resistance and abnormal insulin secretion." (PMID 38440785, 2024). "Insulin resistance for example can develop to a different extent in insulin-sensitive organs such as the liver and skeletal muscle within individuals with obesity, representing different etiologies towards T2D and cardiometabolic risk." (PMID 38594756, 2024). "In the atypical scenario of insulin resistance, the heightened demand for insulin prompts an elevation in insulin secretion, consequently resulting in an augmented co-secretion of islet amyloid polypeptide." (PMID 39135555, 2024).
Insulin resistance (continued). "The metabolic score for insulin resistance (METS-IR) is a neoteric score for assessing insulin resistance that has been used as a non-insulin-based, objectively measured method." (PMID 39469359, 2024). "SGLT2-I, with insulin or insulin secretagogues, enhances insulin resistance, induces hyperinsulinemia, and exacerbates type 2 DM." (PMID 38304078, 2024). "Many horses also suffer from insulin dysregulation (ID), which describes both insulin resistance and the resulting hyperinsulinemia." (PMID 38473112, 2024). "In a cross-sectional study, the relationship between FABP4, insulin secretion, and insulin resistance in 12 T2DM patients and 18 controls was evaluated." (PMID 38731797, 2024). "T2DM is characterized by insulin resistance and chronically elevated high levels of circulating insulin." (PMID 40808720, 2024). "Insulin resistance in MASLD arises from an imbalance between insulin sensitizing adipokines, such as adiponectin and leptin, and cytokines that promote insulin resistance like TNF-α." (PMID 39064282, 2024). "However, insulin resistance, amyloid β (Aβ) deposition, and hyperphosphorylation of Tau lead to disruption of cerebral insulin signaling, which may account for the higher risk of dementia and reduced local efficiency of the parahippocampal gyrus node in patients with T2DM." (PMID 39850732, 2024). "Elevated NEFA disrupt the initial steps of the insulin signaling cascade, exacerbating insulin resistance in peripartum cows." (PMID 39881718, 2024). "A similar process occurs in insulin resistance, where interventions improve insulin signaling, reduce hormone levels, and consequently lower blood glucose levels due to enhanced insulin receptor function." (PMID 39458475, 2024). "Numerous investigations have elucidated the role of ceramides and other sphingolipids in impeding the insulin-signaling pathway in skeletal muscles and the liver, contributing to insulin resistance and T2DM." (PMID 38435063, 2024). "For example, RBM15 was observed to hinder insulin sensitivity and promote insulin resistance through m6A-mediated epigenetic suppression of CLDN4 during the development of gestational diabetes mellitus." (PMID 38765115, 2024). "As insulin resistance intensifies, pancreatic β-cells are pushed to produce more insulin to meet metabolic demands, ultimately leading to β-cell exhaustion and impaired insulin secretion." (PMID 39683465, 2024). "Higher serum C-peptide levels likely reflect the increased insulin secretion due to increased insulin resistance." (PMID 39734999, 2024). "C16:0 is the most abundant fatty acid in the human body, and its abnormal increase within cells can weaken insulin signaling, leading to the development of insulin resistance." (PMID 39713052, 2024). "In this study, we used HOMA-IR to measure insulin resistance from basal (fasting) insulin and glucose concentrations." (PMID 39925819, 2024). "Subsequently, pancreatic cells, liver, and muscle develop insulin resistance due to elevated insulin signaling." (PMID 38902690, 2024). "HOMA-IR and the Matsuda Index, validated in the general population, are commonly used indicators for assessments of insulin resistance and insulin sensitivity, respectively." (PMID 37914981, 2024). "Apparently, these effects (during early development of disease) can cause insulin resistance and mitochondrial dysfunction by obstructing skeletal muscle adaptations in part by reducing the activity of PGC-1α and insulin signaling pathway." (PMID 38044359, 2024). "Insulin resistance impairs the cellular insulin response, and often precedes metabolic disorders, like type 2 diabetes, impacting an increasing number of people globally." (PMID 39572596, 2024). "As a result of the AIDiet intervention conducted in this study, we also observed a beneficial and significant decrease in the HOMA-IR, insulin resistance index and fasting insulin." (PMID 38347150, 2024).
Insulin resistance (continued). "Studies have shown that PNX influences insulin sensitivity and glucose uptake, which are crucial factors in managing insulin resistance in PCOS." (PMID 39398330, 2024). "Previous research has indicated that the deposition of free fatty acids in muscles disrupts insulin signaling, leading to insulin resistance." (PMID 39247920, 2024). "Lipodystrophic patients commonly experience moderate to severe insulin resistance, as leptin and adiponectin are crucial in insulin sensitization." (PMID 38951919, 2024). "High levels of insulin and glucose suggest insulin resistance, which is a major factor in metabolic obesity." (PMID 39275240, 2024). "These vesicles often carry inflammatory cytokines like IL-6 and TNF-α, which interfere with insulin signaling pathways, contributing to insulin resistance." (PMID 39796048, 2024). "Our data show significant differentially regulated gene enrichment in pathways related to insulin resistance and metabolic syndrome: Regulation of eIF4 and p70S6K Signaling, Insulin Secretion Signaling, PPAR Signaling, Leptin Signaling in Obesity." (PMID 38981849, 2024). "In fact, both overexpression and knockdown of ATGL in mouse liver improved insulin action in a setting of HFD-induced insulin resistance." (PMID 38656127, 2024). "In cultured HTR8/SVneo cell, high insulin (10 nM, comparable to the concentration observed in patients with insulin resistance) increased ID2 protein levels while leptin (5–500 ng/mL) did not in these cells." (PMID 39201703, 2024). "Development of insulin resistance, decrease in insulin secretion, and body fat distribution in obesity varies considerably based on ethnicity and dietary habits of people." (PMID 39472276, 2024). "Insulin resistance refers to a decreased metabolic response to insulin in target cells, especially in skeletal muscle, adipose tissue, and liver." (PMID 38751366, 2024). "Excess adiposity, particularly accumulated visceral fat, induces chronic low-grade inflammation and altered adipokine secretions that contribute to insulin resistance and impaired insulin signaling." (PMID 38800249, 2024). "Insulin resistance is thought to lead to hyperglycemia, which then drives pancreatic β cells to secrete more insulin to maintain glucose homeostasis, leading to hyperinsulinemia." (PMID 39769097, 2024). "T2DM is characterized by insulin resistance and insufficient compensatory insulin secretion, the mechanism of which varies by ethnicity." (PMID 38248836, 2024). "Insulin resistance, elevated insulin levels, and activation of the insulin receptor are associated with T2DM." (PMID 38726403, 2024). "Epidemiological evidence supports the notion that people with insulin resistance/hyperinsulinemia have impaired insulin metabolic signaling in vascular cells including ECs and VSMCs, thereby contributing to hypertension and diabetic vasculopathy." (PMID 38255878, 2024). "Insulin resistance requires more insulin to be produced by beta cells to compensate for these desensitized cells." (PMID 38540087, 2024). "Both physically active healthy athletes and sedentary non‐obese individuals with insulin resistance (IR) share some metabolic pathways that are related to exercise and insulin sensitivity." (PMID 37938877, 2024). "IL-6 disrupts insulin signaling by activating pathways that phosphorylate insulin receptor substrates (IRS), leading to reduced insulin receptor activity and insulin resistance, a hallmark of T2DM." (PMID 39857603, 2024). "Excessive fat accumulation leads to the inflammation of adipose tissue, and obesity-associated chronic inflammation alters endocrine variables and interferes with insulin signaling pathways, all of which contribute to insulin resistance." (PMID 39195702, 2024). "Insulin resistance is considered worse by the second half of gestation for both women and bitches, and pregnant bitches are more insulin-resistant than bitches in diestrus." (PMID 38539988, 2024).